IFI16 (interferon gamma inducible protein 16)
Diseases named in the same sentence as IFI16 in open-access papers (continued):
Sharing a sentence is not in itself a finding about the gene and the disease.
Autoimmunity (8 papers, 2011 to 2024). The occurrence of an immune reaction against the organism's own cells or tissues. "We suppose that IFI16 may act as an infection-caused autoantigen involved in the development of autoimmunity." (PMID 30723748, 2019). "Altogether, these data demonstrate that IFI16 may exist as circulating protein in the sera of autoimmune patients which binds endothelial cells causing damage, suggesting a new pathogenic and alarmin function through which this protein triggers the development of autoimmunity." (PMID 23690979, 2013). "As inducer of pro-inflammatory molecules (e.g., ICAM-1, RANTES, and CCL20) and apoptosis in primary endothelial cells, IFI16 might be active during the initial phases of the inflammatory processes paving the way to the onset of autoimmunity." (PMID 29892303, 2018). "In this context, it is important to note that IFI16, normally expressed in cell nuclei, may be overexpressed in several autoimmune disorders." (PMID 26271464, 2015). "Therefore, the release of IFI16 in the extracellular milieu may mark the first step in the development of autoimmunity." (PMID 26271464, 2015).
osteosarcoma (8 papers, 2010 to 2023). A usually aggressive malignant bone-forming mesenchymal neoplasm, predominantly affecting adolescents and young adults. "ChIP studies demonstrated the presence of IFI16 bound to HSV-1 promoters in osteosarcoma (U2OS) cells and fibroblasts." (PMID 25375629, 2014). "Forced overexpression of IFI16 protein in Saos2 (a human osteosarcoma cell line) cells down-regulated the expression of c-MYC gene." (PMID 20052289, 2010). "Moreover, our ongoing studies with HSV-2 and HSV-1 with human osteosarcoma cells in which IFI16 is knocked out by CRISPR demonstrate that in the absence of IFI16, the IFN-β response is significantly abrogated." (PMID 27764250, 2016). "Additionally, overexpression of IFI16 protein in human osteosarcoma cell line Saos-2 down-regulated the expression of c-MYC and RAS genes." (PMID 20052289, 2010). "Finally, to circumvent potential issues of structural or functional differences between mammalian or bacterial expressed IFI16, we used wild-type and IFI16-knockout (IFI16-/-) human osteosarcoma U2OS cells as a source of endogenous IFI16 released under stress stimuli." (PMID 32903274, 2020). "Here, we show that IFI16 has a profound effect on HSV-1 replication in human foreskin fibroblasts, osteosarcoma cells, and breast epithelial cancer cells." (PMID 25375629, 2014). "To further confirm these results, we used IFI16 CRISPR knockout (KO) osteosarcoma U2OS cells (U2OS 67) generated in our earlier studies to study the effect of IFI16 KO and re-introduction of IFI16 in a KO background on the recruitment of H3K9me3, SUV39H1 and GLP." (PMID 31682228, 2019). "In addition, IFI16 repressed the transcription of KSHV luciferase promoter constructs in the uninfected epithelial SLK and osteosarcoma U2OS cells." (PMID 31682228, 2019).
psoriasis (8 papers, 2016 to 2025). An autoimmune condition characterized by red, well-delineated plaques with silvery scales that are usually on the extensor surfaces and scalp. "Nevertheless, further studies of IFI16 are needed to fully clarify the pathogenic role of IFI16 and evaluate its potential to be a therapeutic target in psoriasis." (PMID 27137868, 2016). "However, whether IFI16 plays a pathogenic role in psoriasis and the underlying mechanism remains unknown." (PMID 27137868, 2016). "In conclusion, we demonstrate that the cytokines-mediated overexpression of IFI16 contributes to the pathogenesis of psoriasis by activating the TBK1-NF-κB signaling pathway and then inducing the production of CXCL10 and CCL20 in keratinocytes." (PMID 27137868, 2016). "Our findings consider IFI16 functions as a central hub in the initiation of immune response in psoriasis." (PMID 27137868, 2016). "Given that IFI16 is overexpressed in psoriatic keratinocytes and keratinocyte activation is related to psoriasis, we conjectured that IFI16 contributes to the development of psoriasis by modulating keratinocyte function." (PMID 27137868, 2016). "This study demonstrated that IFI16 was highly expressed in the epidermis of lesions from psoriasis patients." (PMID 27137868, 2016). "Frist, we examined the expression of IFI16 in the epidermis and dermis of skin samples obtained from psoriasis patients and normal donors." (PMID 27137868, 2016). "In the present study, we cinfirmed that IFI16 was overexpressed in epidermal keratinocytes of psoriasis patients." (PMID 27137868, 2016). "Meanwhile, the psoriasis lesions were improved when IFI16 expression was inhibited." (PMID 40560938, 2025). "In addition, IFI16 was highly expressed in the skin lesions that imiquimod-induced psoriasis mouse model." (PMID 40560938, 2025). "It shows that IFI16 plays an important role in the pathogenesis and treatment of psoriasis." (PMID 40560938, 2025). "In addition, abnormal IFI16 expression has been also detected in the skin of individuals affected by systemic sclerosis (SSc) or psoriasis (Pso), as well as in salivary epithelial cells and infiltrating lymphocytes of subjects with Sjögren’s syndrome (SS)." (PMID 32903274, 2020). "Furthermore, the immunohistochemistry and immunofluorescence staining revealed that IFI16 was expressed only in the basal layer of normal skin, but highly expressed in the thickened epidermis of psoriasis patients, primarily in the nuclei of keratinocytes." (PMID 27137868, 2016). "To test this hypothesis, we assessed IFI16 expression in the lesions of psoriasis patients, and examined the mechanism of IFI16-mediated keratinocyte activation in vitro." (PMID 27137868, 2016). "Further, we used siRNA to knock down p204 in a mouse model of imiquimod (IMQ)-induced psoriasis-like dermatitis, identifying that IFI16 could promote the development of psoriasis in vivo." (PMID 27137868, 2016). "The immunohistochemistry analysis also revealed that p204 expression was increased in the epidermis of mice’s skin lesions after IMQ treatment, implying that IFI16 (p204) contributed to the development of psoriasis not only at a very early stage, but also throughout the whole disease progression." (PMID 27137868, 2016). "Therefore, our results indicate that IFI16 plays a critical role in keratinocyte activation in psoriasis." (PMID 27137868, 2016). "We therefore hypothesized that IFI16 promotes psoriasis by modulating keratinocyte activation." (PMID 27137868, 2016). "In summary, the study identified a series of characteristic genes (DEFB103A, IFI16, OAS3, OASL, SAMD9, STAT1, etc.)that are highly related to the occurrence, treatment of psoriasis." (PMID 40560938, 2025). "Based on our results; AIM2 and IFI16 are highly expressed inflammasome receptors in psoriasis, whereas NLRP3 was not among the DEGs." (PMID 26976200, 2016).
psoriasis (continued). "In addition, psoriasis-related cytokines, including IFN-γ, TNF-α, IL-17 and IL-22, induced IFI16 up-regulation in keratinocytes via activation of STAT3 signaling." (PMID 27137868, 2016). "In vitro results showed that several psoriasis-related cytokines, including IFN-γ, TNF-α, IL-17 and IL-22, could up-regulate IFI16 expression in keratinocytes via activation of STAT3 signaling." (PMID 27137868, 2016). "Therefore, we focused on the biologic functions of IFI16 in the progression of psoriasis, but not its subcellular localization." (PMID 27137868, 2016). "e., overexpression of IFI16 in otherwise negative cells or IFI16 delocalization to the cytoplasm—has been reported in a number of inflammatory conditions, such as SLE (skin), psoriasis (skin), SSc (skin), IBD (colonic epithelium) and SS (salivary epithelial and inflammatory infiltrating cells)." (PMID 32903274, 2020).
latent infection (7 papers, 2016 to 2025). "Since IFI16 promotes immediate early gene expression it is conceivable that its downmodulation might promote the establishment of a latent infection." (PMID 33353088, 2020). "Having established that US28 downregulates IFI16 early during the establishment of latency, we wanted to address why this may be beneficial to the virus for latent infection." (PMID 31796538, 2019). "Having confirmed that IFI16 is downregulated very early during latent infection of monocytes, we then sought to establish whether this effect is dependent on US28." (PMID 31796538, 2019). "Since we observed IFI16 and H2B interaction in the nucleus of uninfected B (BJAB) cells, we next determined their association and distribution during KSHV latent infection in B cells." (PMID 27764250, 2016). "Moreover, IFI16 is also crucial for the latent infection of HHVs." (PMID 35337341, 2022). "IFI16 is associated with the nuclear sensing of herpesvirus DNA (27, –, 31) and control of herpesvirus gene expression (32, –, 39) and also represses viral transcription during HIV latency, but the effects of IFI16 on HCMV latent infection are unknown." (PMID 31796538, 2019). "We also observed similar findings and in addition, demonstrate the interactions of cGAS with H2B, IFI16, BRCA1, and STING in the cytoplasm of cells during de novo infection as well as in latent infection." (PMID 27764250, 2016). "Additionally, IFI16 has been shown to activate NFkB signalling and, during HCMV latent infection, downregulation of IFI16 by US28 appears to suppress NFkB-mediated activation of the MIEP, thereby helping to maintain latency." (PMID 32698381, 2020). "IFI16 has initially been shown to bind to the KSHV genome during both de novo and latent infection and might be required for maintaining the virus in a latent state." (PMID 33353088, 2020). "Taken together, our results indicate that US28 rapidly downregulates IFI16 during latent infection of monocytes, but not during lytic infection of mature dendritic cells." (PMID 31796538, 2019). "Collectively, these results demonstrated the association of STING with IFI16 and H2B but not with ASC in the cytoplasm during KSHV de novo and latent infection." (PMID 27764250, 2016). "Nevertheless, these findings suggest that IFI16, H2B, BRCA1, cGAS and STING associate in the cytoplasm during KSHV de novo and latent infection that is independent of ASC." (PMID 27764250, 2016).
rheumatoid arthritis (7 papers, 2020 to 2024). A chronic, systemic autoimmune disorder characterized by inflammation in the synovial membranes and articular surfaces. "Higher anti-IFI16 antibody levels have already been associated with other inflammatory diseases such as SLE, rheumatoid arthritis, and psoriatic arthritis." (PMID 35733868, 2022). "Noteworthy, serum circulating IFI16 protein and its specific autoantibodies have also been reported in various autoimmune diseases, including SSc, rheumatoid arthritis (RA), SLE, SS, psoriatic arthritis (PsA) and IBD." (PMID 32903274, 2020).
systemic sclerosis (7 papers, 2016 to 2024). A chronic disorder, possibly autoimmune, marked by excessive production of collagen which results in hardening and thickening of body tissues. "They found that the expression of IFI16 was greatly increased and ubiquitous in all layers of the epidermis in lesioned skin from both patients with SLE and those with systemic sclerosis." (PMID 37393341, 2023).
inflammatory bowel disease (6 papers, 2018 to 2023). A spectrum of small and large bowel inflammatory diseases of unknown etiology. "In active inflammatory bowel disease, a significant two‐fold higher expression of AIM2 and IFI16 is observed in the intestinal mucosa compared with controls, indicating priming/upregulation of these proteins in certain conditions involving barrier function integrity." (PMID 31850638, 2020).
leukemia (6 papers, 2016 to 2025). A malignant (clonal) hematologic disorder, involving hematopoietic stem cells and characterized by the presence of primitive or atypical myeloid or lymphoid cells in the bone marrow and the blood. "Upon AOSD-NETs stimulation, the human leukemia monocytic cell line THP1 showed enhanced expression of IFI16 and DDX60 relative to HC-NETs, which was consistent with the expression pattern observed in AOSD patients." (PMID 38124139, 2023). "In this study, we found that curcumin induced the expression of NLRC4, AIM2, and IFI16 inflammasomes by upregulated ISG3 transcription factor complex in leukemia cell U937, which activates caspase 1 and promotes cleavage of GSDMD." (PMID 35435150, 2022). "In summary, here we have discovered that curcumin can induce leukemia cell death by increasing apoptosis and pyroptosis and that activated AIM2, IFI16, and NLRC4 inflammasomes play a key role in this process." (PMID 35435150, 2022). "In this study, we demonstrated that curcumin induced the expression of AIM2, IFI16, and NLRC4 inflammasomes in leukemia cells U937 by increasing the expression levels of ISG3 transcription factor complex, which activated caspase 1, promoted cleavage of GSDMD, and induced pyroptosis." (PMID 35435150, 2022). "Human IFI16, an ortholog of the mouse BC094916 gene, was shown to localize to the nucleus of 293T cells, lymphoma line Daudi cells, and IFNγ-treated cells of the leukemia line HL-60." (PMID 30220882, 2018). "Herpes simplex virus-1 (HSV-1) is the best-studied model in this context, and it was shown that upon nuclear entry HSV-1 genomes are immediately targeted by components of promyelocytic leukemia nuclear bodies (PML-NBs) and the nuclear DNA sensor IFI16 (interferon gamma inducible protein 16)." (PMID 27782081, 2016).
Obesity (6 papers, 2018 to 2025). Accumulation of substantial excess body fat. "IFI16 and its murine homologs, particularly IFI202b, have been implicated in the development and regulation of obesity." (PMID 39158380, 2025). "The aim of the current work was to provide direct functional evidence for Ifi202b as an obesity gene and to clarify the role of its human orthologue IFI16 in obesity-associated insulin resistance." (PMID 29478099, 2018). "High levels of IFI16 in human adipose tissue are associated with larger adipocyte size and reduced insulin‐stimulated glucose uptake, suggesting a link between IFI16 expression and metabolic dysfunction in obesity." (PMID 39158380, 2025). "The mouse Ifi205 and Ifi202b are closely related to human IFI16 and have been studied extensively to understand their roles in obesity." (PMID 39158380, 2025). "IFI16 and its murine homologs, particularly IFI202b, play significant roles in the development of obesity through their effects on adipocyte differentiation, insulin resistance, and inflammation." (PMID 39158380, 2025). "The levels of IRF7-associated ISG-encoding transcripts, including IFI16, ZBP1 and TMEM173 (STING1), were increased in the adipose tissue of children with obesity, reflecting their elevated IRF7 levels." (PMID 36443525, 2022). "Our findings reveal novel functions of Ifi202b and IFI16, demonstrating their role as obesity genes." (PMID 29478099, 2018). "Our data provide direct functional evidence for the role of Ifi202b/IFI16 as an obesity gene and shows that it adjusts adipocyte commitment, maintenance of white adipocyte identity, fat cell size and the inflammatory state of adipose tissue." (PMID 29478099, 2018). "Furthermore, the authors found that overexpression of Ifi16 in mice led to obesity." (PMID 38139000, 2023). "In this review, we summarize the current knowledge on the roles of TLR9, cGAS‐STING, AIM2, IFI16, DNA‐PK, and DDX41 in obesity, diabetes, fatty liver disease, and cardiovascular disease." (PMID 39158380, 2025). "IFI16, ERBB2, VIM (vimentin) and CAV1 are crucial factors for advancement of obesity." (PMID 36837510, 2023). "Expression of Ifi16 is significantly decreased in Il18−/− mice, which leads us to speculate that Ifi16 might not be related to obesity in Il18−/− mice." (PMID 38139000, 2023).
periodontitis (6 papers, 2020 to 2026). An acute or chronic inflammatory process that affects the tissues that surround and support the teeth. "Among them, only Ifi204, the murine homolog of human IFI16, showed consistent inhibition of expression in the DeP and CgP, which regulates the release of IL-1β in tissues and plays a vital role in bone loss in experimental periodontitis." (PMID 37008900, 2023). "Polymorphisms in various inflammasome components, including NLRP3, AIM2, and IFI16, may be associated with susceptibility to periodontitis." (PMID 34177950, 2021). "The mRNA levels of murine Ifi204, which has a structure and function similar to those of human IFI16, were also increased in gingival tissues of ligature-induced periodontitis." (PMID 34177950, 2021). "Further analysis by our group showed that multiple genes encoding inflammasome components, including Aim2, Ifi204 (the mouse homolog of IFI16), and Nlrp3, exhibit increased expression in gingival tissues of murine experimental periodontitis." (PMID 32533779, 2020). "Additionally, migrating neutrophils expressing IFI16 and AIM2 were observed in the epithelial layer in gingival tissues derived from individuals with periodontal disease, further supporting a potential role of these proteins in the pathogenesis of periodontitis." (PMID 32533779, 2020).
COVID-19 (5 papers, 2021 to 2025). A disease caused by infection with severe acute respiratory syndrome coronavirus 2. "OASL, RSAD2, ISG20, IFI16, and IFIT1 were not previously annotated in the COVID-19 KEGG pathway." (PMID 38580667, 2024).
colorectal cancer (4 papers, 2016 to 2022). A primary or metastatic malignant neoplasm that affects the colon or rectum. "IFI16 has been shown to influence ribosome biogenesis and has been identified as a promoter associated with stem cell-like properties in colorectal cancer." (PMID 35571562, 2022). "The expression of mRNA encoding IFI16, STING, TBK1, and IFN-β was significantly decreased in the colorectal cancer tissues in comparison to normal tissue in a cohort of Chinese colorectal cancer patients." (PMID 28748479, 2018).
influenza (4 papers, 2016 to 2025). An acute viral infection of the respiratory tract, occurring in isolated cases, in epidemics, or in pandemics; it is caused by serologically different strains of viruses (influenzaviruses) designated A, B, and C, has a 3-day incubation period, and usually lasts for 3 to 10 days. "Recently, it was shown that IFI16 is activated directly by influenza RNA, causing an enhancement of RIG-I transcription and activation, potentially leading to restriction of influenza infection." (PMID 36298668, 2022). "We recently demonstrated that upon sensing of influenza by RIG-I and HCMV by IFI16, CEACAM1 expression is induced." (PMID 27634893, 2016). "Multiple inflammasomes can be involved in IL-1β activation, including NLRP3, NLRP1, NLRC4, AIM2, IFI16 and RIG-I, however because GC B cells are not directly infected by influenza infection, we examined NLRP3 and AIM2 as they are activated by stimuli likely to be present in GC B cells." (PMID 40825032, 2025).
lentivirus infection (4 papers, 2019 to 2024). Virus diseases caused by the Lentivirus genus. "We treated these MIEP-eGFP THP-1 cells with control lentiviruses or lentiviruses which drive the overexpression of IFI16, ensuring equivalent lentivirus infection of reporter cells by a p24 enzyme-linked immunosorbent assay (ELISA)." (PMID 31796538, 2019). "We validated the efficiency of lentivirus infection through RT-qPCR and western blotting experiments, ensuring high or low expression of IFI16 at the transcription and translation levels." (PMID 38831470, 2024).